FOXP3 (forkhead box P3)
Diseases named in the same sentence as FOXP3 in open-access papers (continued):
Sharing a sentence is not in itself a finding about the gene and the disease.
cutaneous melanoma (12 papers, 2007 to 2023). A primary melanoma arising from atypical melanocytes in the skin. "To evaluate the subtypes of immunosuppressive cells associated with progression of cutaneous melanoma, we measured FOXp3, a transcription factor found in both suppressor and regulatory T lymphocytes, and ILT3 and ILT4 that are associated with tolerogenic DCs." (PMID 17565341, 2007). "Next, we analyze the correlation between LFA-1 and Treg cells specific nuclear transcription factor (Foxp3) in skin cutaneous melanoma(SKCM) and immune cell infiltration in the TIMER tumor database." (PMID 37723552, 2023). "The results show that MVD, TILs and FOXP3+ Tregs substantially influence cutaneous melanoma microenvironment." (PMID 25913374, 2015). "In summary, the results show that MVD, TILs and FOXP3+ Tregs are substantially involved in the alteration of the cutaneous melanoma microenvironment." (PMID 25913374, 2015). "Compared to one study of cutaneous melanoma metastasis, the density of CD3 and CD68CD163 was similar, with a higher density of CD4 and Foxp3, and lower density of CD8 cells." (PMID 28903377, 2017). "FoxP3+ Regulatory T cells (Tregs) and indoleamine-2,3-dioxygenase (IDO) participate in the formation of an immunosuppressive tumor microenvironment (TME) in malignant cutaneous melanoma (CM)." (PMID 34051744, 2021). "The Treg transcription factor FOXP3 was significantly lower (p < 0.01), while CD25 (IL2RA) was significantly higher (p < 0.0001) in PDAC (n = 147) than in skin cutaneous melanoma (n = 472) indicating that CD25 is expressed in PDAC by non-regulatory T cells as well." (PMID 27762323, 2016). "Analysis of transcriptomic data from a skin cutaneous melanoma (SKCM) data set (n = 472), using skin biopsy of healthy women (n = 122) as a reference, showed that upregulation in TGFβ signaling strongly correlated with increased messenger RNA expression levels of TGFB1 and FOXP3." (PMID 29467463, 2018).
depression (12 papers, 2016 to 2025). "We investigated associations between FoxP3+ Tregs and Treg subpopulations and symptoms of depression, state anxiety, pregnancy-related anxiety, and perceived stress in a cohort of pregnant women living in the greater Los Angeles area." (PMID 38016492, 2024). "Another found that women with postpartum depression two weeks after birth had higher levels of FoxP3+ Tregs relative to healthy controls during pregnancy and the postpartum." (PMID 38016492, 2024). "A study used multiparameter flow cytometry to identify CD4+CD25+ Tregs and CD4+ CD25+FOXP3+ Tregs in major depressive disorder." (PMID 37238593, 2023). "It is difficult to interpret unambiguously the phenomenon of Foxp3 levels dropping in patients with depression." (PMID 33498653, 2021). "This is consistent with the results of our experiment, which showed that the average mRNA expression for the Foxp3 gene was significantly reduced in patients with depressive disorders." (PMID 33498653, 2021). "The mean mRNA expression of Foxp3 was considerably reduced in patients suffering from depressive disorders." (PMID 33498653, 2021). "The experiment shows that IL-17, IL-21, IL-23, IL-35 and Foxp3 concentration can be a marker in the diagnosis of depressive disorders." (PMID 33498653, 2021). "Whereas diminished thymic function and dysfunction of immune regulation by FoxP3+ Tregs is well recognized in stress-induced depression in mice, less is known in human anxiety and particularly panic disorder." (PMID 27362416, 2016). "Moreover, the Th17/Treg transcription factor RoRα/FoxP3+ was significantly and negatively correlated with 5-HT contents, while it was positively correlated with depression-like behaviors." (PMID 36430328, 2022). "The levels of IL-17 gene expression among 190 patients with depression were higher compared to 100 healthy individuals, while the mean mRNA expression of the immunoregulatory Foxp3 was considerably reduced in patients suffering from depressive disorders compared to the control group." (PMID 34367160, 2021). "However, the mean expression for IL-21, IL-35 and of the Foxp3 gene at mRNA level was significantly reduced in the patients with depressive disorders." (PMID 33498653, 2021). "Here we have now shown the effects of chronic stress (hip fracture and depression) on two regulatory immune cell subsets; CD4+CD25+Foxp3+ (Tregs) and CD19+CD24hiCD38hi (Bregs) and again find that depressive symptoms are the factor determining the immune alterations." (PMID 26112234, 2016). "In males, methylation was higher at specific CpGs in the FOXP3 enhancer region in smokers as well as in patients with comorbid depression compared to non-smoking patients or patients without depression, respectively." (PMID 27362416, 2016). "Multiple regression analysis (R2 = 0.345; p = 0.032) showed that methylation at FOXP3 enhancer, sequence 2, CpG 5 was weakly influenced by smoking (p = 0.067) and older age (p = 0.073) but not by depression (p = 0.267) or antidepressants (p = 0.868)." (PMID 27362416, 2016). "Categorization of female patients into smokers, into patients with depression and into patients on antidepressants did not reveal any differences in FOXP3 enhancer methylation." (PMID 27362416, 2016). "However, pre-treated rats with hesperidin could significantly increase the population of CD4+CD25+Foxp3+Treg in OVA-induced bronchial asthma and depression." (PMID 37950769, 2024). "In male patients, significantly higher methylation was determined at FOXP3 enhancer, sequence 2, CpG 4 (0.84 ± 0.70%) and 5 (1.16 ± 1.33%) in the case of depression compared to male patients without depression (position 4 (0.51 ± 0.37%) and 5 (0.51 ± 0.33%); p = 0.039 and p = 0.006, respectively)." (PMID 27362416, 2016).
gastric tumor (12 papers, 2015 to 2023). "In gastric tumors, only high FoxP3+ density was significantly associated with a prolonged OS in the univariable model, but this association did not remain significant in the multivariable analysis." (PMID 29069772, 2017). "have demonstrated that the percentage of Foxp3+ Tregs in the gastric tumor microenvironment is correlated with the prognosis." (PMID 36814928, 2023). "We suggest that GO-Y022 cooperates with 2DG-treatment strongly to prevent TGF-β and L-lactate production, therefore Foxp3+Treg generation of in the gastric tumor microenvironment was significantly reduced in the presence of GO-Y022 and 2DG." (PMID 36814928, 2023). "Elevated FOXP3 expression has also been found in the gastric tumor specimens and lymph nodes from patients with metastatic gastric cancer." (PMID 35037550, 2022). "Furthermore, FOXP3 protein expression was detected by immunohistochemistry and western blot in human parenchymal cells from cervical esophageal cancer, gastric tumor cells, and invasive ductal breast carcinoma." (PMID 34484217, 2021). "However, GO-Y022 showed less impact on Foxp3+ Tregs in the gastric tumor microenvironment." (PMID 36814928, 2023). "In the present study, the immunosupresive microenvironment of gastric tumor tissue was positively correlated with the number of intratumor FoxP3+ Tregs, which indicates that intratumor FoxP3+ Tregs may play an important role in the promotion of these immunosupresive conditions." (PMID 31417548, 2019). "Gastric tumor cells produce enormous quantities of TGF-β and induce Foxp3+Tregs, which negatively regulate anti-tumor immunity." (PMID 36814928, 2023). "Next, we performed a co-culture experiment using gastric tumor cells and human naïve CD4+ T cells to examine the ability of Foxp3+ Tregs generation in the tumor microenvironment." (PMID 36814928, 2023). "Transforming growth factor beta 1 (TGF-β1) induces Foxp3+ regulatory T cells (Tregs), and TGF-β1 from gastric tumors inhibits anti-tumor immunity in the tumor microenvironment via this mechanism." (PMID 36814928, 2023). "We further validated this result in an independent international cohort using a tissue microarray (TMA) comprising 84 gastric tumor core samples by mIHC of CD8+, FOXP3+ and PD‐L1+ cells." (PMID 32377339, 2020). "Since GO-Y022-treated gastric tumor cells produce large amounts of L-lactate, GO-Y022 in this co-culture system did not prevent Foxp3+ Treg generation of in the tumor microenvironment." (PMID 36814928, 2023). "We observed these non‐Treg CD4+FOXP3+ T cells exist in the gastric tumor tissue (data not shown) and up‐regulation of IFN‐γ response genes in the High‐High tumors." (PMID 32377339, 2020).
juvenile idiopathic arthritis (12 papers, 2011 to 2023). Juvenile idiopathic arthritis (JIA) is the term used to describe a group of inflammatory articular disorders of unknown cause that begin before the age of 16 and last over 6 weeks. "The majority of CD25lowFOXP3+ cells sorted from synovial fluid mononuclear cells of juvenile idiopathic arthritis patients were shown to have a demethylated FOXP3 TSDR, suggesting that this subset may be enriched at inflammatory sites." (PMID 28747257, 2017). "In this study, we report that, unlike in peripheral blood, CD4+ T cell expression of CD25 and FOXP3 is frequently dissociated at the inflamed site in patients with juvenile idiopathic arthritis, which led us to question the stability of human Tregs in chronic inflammatory environments." (PMID 25092890, 2014). "The aim of this article is to provide an overview of the literature reporting Foxp3+ Regulatory T cell (Treg) cell biology in juvenile idiopathic arthritis (JIA) and place this in the context of recent advances in understanding basic Treg biology." (PMID 30333832, 2018). "Our study demonstrates, therefore, that hypomethylation at the TSDR can be decoupled from FOXP3 expression in human T cells and that environment-specific breakdown in FOXP3 stability may compromise the resolution of inflammation in juvenile idiopathic arthritis." (PMID 25092890, 2014). "A key paradox often encountered in studies of autoimmune disease, exemplified by childhood arthritis (Juvenile Idiopathic Arthritis [JIA]), is the enrichment of FOXP3+ T cells at the inflamed site." (PMID 25092890, 2014). "In juvenile idiopathic arthritis (JIA) patients, we have previously reported that atypical CD25+FOXP3− Treg-like cells uniquely populate the inflamed site." (PMID 26561546, 2015).
liver fibrosis (12 papers, 2014 to 2024). "The liver fibrosis and splenic diseases caused by S. japonicum are associated with the great number of FOXP3+ Tregs in the blood." (PMID 33628844, 2021). "This is consistent with previous studies which have demonstrated that a higher number of FOXP3+ cells are present in livers of HCV‐infected patients, and that FOXP3+ Treg play an important role in this condition, compared with other causes of liver fibrosis." (PMID 24597693, 2014). "Foxp3+ regulatory T (Treg) cells are pivotal in maintaining immunological self-tolerance and tissue homeostasis; however, it remains unclear how tissue Treg cells respond to liver injury and regulate chronic inflammation, which can cause liver fibrosis." (PMID 33178216, 2020). "The results showed that liver fibrosis caused a significant increase in the proportion of CD4+ IFN-γ+ T-cells (Th1), CD4+ IL-17A+ T-cells (Th17), and CD4+ CD25+ Foxp3+ Tregs, compared with the control group (p < 0.05)." (PMID 34158112, 2021). "The literature also provides data that correlate FOXP3 expression and the presence of Treg cells with higher levels of inflammatory activity and the degree of liver fibrosis in chronic viral hepatic diseases." (PMID 30233595, 2018). "In a recent study, the contribution of Treg cells in the inflammation induced by viral hepatitis has revealed a noteworthy implication of the FOXP3 SNP rs3761547 T > C. It has displayed a significant influence on the progression of hepatic fibrosis induced by viral hepatitis." (PMID 39117877, 2024). "Indeed, within HCV patients, hepatic CD4+Foxp3+ T cells are negatively correlated with liver fibrosis, whereas CD4+Foxp3+ Tregs in the blood of chronic HCV patients are less frequent than in healthy controls." (PMID 33869241, 2021).
Lymphadenopathy (12 papers, 2008 to 2025). Enlargement (swelling) of a lymph node. "A similar syndrome is caused by the naturally occurring Foxp3 mutation in mice resulting in the scurfy phenotype characterized by diarrhea, runting, a scaly skin rash, anemia, thrombocytopenia, lymphadenopathy, hepatosplenomegaly, and early death." (PMID 30443250, 2018).
osteosarcoma (12 papers, 2014 to 2025). A usually aggressive malignant bone-forming mesenchymal neoplasm, predominantly affecting adolescents and young adults. "In a study of osteosarcoma, anti-PD-1 treatment increased overall survival and decreased intra-tumoral Ki67+Foxp3+CD4+ Treg cells in osteosarcoma-bearing mice, compared with sham-treated control." (PMID 39247203, 2024). "In the TARGET‐osteosarcoma cohort, we observed a strong correlation between the LAMP3_DC gene signature and the CD4_C6_FOXP3 and CD4_C5_CXCL13 cellular gene signatures." (PMID 36305631, 2022). "Neuroblastoma and ganglioneuroblastoma scored the highest FoxP3 median values, whereas neproblastoma and osteosarcoma showed the lowest levels, respectively." (PMID 31922656, 2020). "Parameters included in systematic evaluation of staining conditions for CD31, CD8 and FOXP3 in osteosarcoma samples." (PMID 24594971, 2014). "In 20 representative osteosarcoma samples whole-slide numbers of FOXP3+ cells ranged from 0,003 to 4,1 cells/0,1 mm2 with a median of 0,73 cells/0,1 mm2±1,06 (SEM)." (PMID 24594971, 2014). "Systematic evaluation of different antigen retrieval protocols revealed high pressure heat-induced epitope retrieval in combination with polymer detection as a reliable method for detection of CD8 and FOXP3 in decalcified osteosarcoma sections." (PMID 24594971, 2014). "In this study, we identified a heterogeneous but functionally constrained T/NK ecosystem in osteosarcoma, where enrichment of FOXP3+ Tregs and exhausted CD8+ T cells paralleled recent single-cell atlases that describe pervasive T-cell dysfunction and regulatory dominance." (PMID 41346635, 2025). "Correlation between LAMP3_DCs and FOXP3+ Tregs was observed in primary osteosarcoma tumour tissues, suggesting that LAMP3_DC may contribute to immune tolerance in osteosarcoma tumours through recruiting and regulating FOXP3+ Tregs." (PMID 36305631, 2022). "Moreover, osteosarcoma patients with elevated CD8(+)/FOXP3(+) ratio and CD8+/Treg ratio in TME often harvest improved survival." (PMID 32000789, 2020). "In fact, under these conditions FOXP3+ cells could be detected in 98% of 120 analyzed osteosarcoma samples which could further be evaluated." (PMID 24594971, 2014). "Reassessment of the immunostained osteosarcoma cross sections revealed a homogeneous distribution of FOXP3 immunoreactive cells in 70% of 120 samples which might explain this correlation." (PMID 24594971, 2014). "Moreover, false low staining for CD31 and FOXP3 was detected in the vast majority of analyzed osteosarcoma samples." (PMID 24594971, 2014). "Interestingly, NECTIN2–TIGIT interaction was enriched in proliferating TAMs and CD4_C3_CXCL13, CD4_C3_FOXP3 and CD8_C2_GNLY cell sub‐clusters, indicating that Proli_TAM may lead to T cell exhaustion in osteosarcoma PT tissues." (PMID 36305631, 2022). "However, in case of more homogeneous distributed antigens like FOXP3, quantification by whole-slide analysis and hot spot analysis provide comparable results, as shown by a significant correlation in a representative cohort of 20 osteosarcoma specimens." (PMID 24594971, 2014). "The presented protocols established during our study for cell surface antigens (CD31, CD8) and intracellular/nuclear antigens like FOXP3 might be also used for other antigens in formalin-fixed and paraffin-embedded osteosarcoma samples and probably other tumors." (PMID 24594971, 2014). "Using multiplex fluorescence staining methods, we observed co‐localization of CD4+FOXP3+ Tregs and LAMP3+ DC in osteosarcoma tissues, which indicated the recruitment of Tregs by LAMP3_DC as previous reports." (PMID 36305631, 2022). "Interestingly, T lymphocytes are the one of major immune cells infiltrated in osteosarcoma tissues, and high CD8+ T lymphocytes/FOXP3 cells ratio predicted better prognosis." (PMID 34383385, 2022).
osteosarcoma (continued). "These cells also recruited CD4_C4_FOXP3 through CD86‐CTLA4, which may contribute to the immune evasion of tumour cells in osteosarcoma TME." (PMID 36305631, 2022). "Conventional detection of CD31+ micro vessels was false negative in 35% out of 120 high grade central osteosarcoma specimens, and was false negative for FOXP3 positive cells in 65% out of a representative group of 20 osteosarcoma samples." (PMID 24594971, 2014). "We considered CD31, CD8 (cell surface epitopes) and FOXP3 (intracellular epitope) as immunovascular biomarkers of major interest in osteosarcoma, representing intratumoral vessels (CD31), tumor attacking T-cells (CD8) and immunosuppressive or anergic T-cells (FOXP3)." (PMID 24594971, 2014). "However, in osteosarcoma, rhabdomyosarcoma and nephroblastoma, there was a significant density correlation between PD‐L1 levels and the counts of the T‐cell markers CD3, CD8, and FoxP3, and to a lesser extent with CD45RO." (PMID 31922656, 2020). "However, when we applied this protocol on osteosarcoma specimens, we retrieved inconsistent staining intensities with false low detection of FOXP3 positive cells in 35%, and negative detection of FOXP3 positive cells in 65% of all tested samples (n = 20)." (PMID 24594971, 2014).
primary immunodeficiency (12 papers, 2012 to 2025). "For example, immunodysregulation polyendocrinopathy enteropathy X-linked (IPEX) syndrome is a primary immunodeficiency and the dysfunction arises from mutations in FOXP3 leading to APA." (PMID 37006267, 2023). "Due to the Foxp3 protein’s involvement in the regulation of transcription, we will try to explain its role in the development of primary immunodeficiency diseases that are strongly associated with genetic disorders." (PMID 35207219, 2022). "In the present review two patients with autoimmune enteropathy were affected by IPEX, a primary immunodeficiency caused by mutations in FOXP3 gene, which encodes an essential transcription factor required for maintenance of thymus-derived regulatory T cells." (PMID 33673586, 2021). "Immune dysregulation, polyendocrinopathy, enteropathy, X-linked (IPEX) syndrome is a rare monogenic primary immunodeficiency (PID) due to mutations of FOXP3, a key transcription factor for naturally occurring (n) regulatory T (Treg) cells." (PMID 23060872, 2012). "The current Working Definitions for Clinical Diagnosis of Primary Immunodeficiency recommend studying FoxP3 expression in CD4+CD25hi cells." (PMID 38077340, 2023). "However, a full understanding of the role of Foxp3 in the development of CVID requires further extensive interdisciplinary research to understand its role in the pathogenesis of primary immunodeficiencies." (PMID 35207219, 2022).